TLR4 (toll like receptor 4)
Diseases named in the same sentence as TLR4 in open-access papers (continued):
Sharing a sentence is not in itself a finding about the gene and the disease.
Hypertension (continued). "In conclusion, our findings demonstrate that increased TLR4 expression may play an important role in arterial hypertension." (PMID 22233532, 2012). "Vascular risk factors (hypertension, type 2 DM, and hypercholesteremia) did not significantly modify the association between TLR4 polymorphisms and the risk of LOAD." (PMID 23272070, 2012). "Association between TLR4 SNPs and LOAD risk by hypertension status." (PMID 23272070, 2012). "However, the contribution of cardiac specific TLR4 to the development of hypertension and cardiac remodeling is unknown." (PMID 37034342, 2023). "Further studies in female mice are warranted to determine whether sex differences exist regarding the expression of TLR4 in cardiomyocytes of hypertensive hearts and specific contribution of cardiomyocyte TLR4 inhibition on hypertension and cardiovascular function." (PMID 37034342, 2023). "In this study we investigate whether cardiomyocyte specific TLR4 deletion will be able to attenuate the profibrotic, proinflammatory, deleterious cardiac function and physiological measurements of angiotensin (Ang) II-induced hypertension." (PMID 37034342, 2023). "Therefore, we hypothesized that cardiomyocyte specific knockdown of TLR4 would have beneficial effects on hypertension, cardiac hypertrophy, and remodeling." (PMID 37034342, 2023). "However, further in-depth studies are needed to determine the direct evidence of NKA α2 regulation of their downstream pathways that regulates Rac1-dependent oxidative stress and TLR4-induced inflammation in the PVN during the development of high salt-induced hypertension." (PMID 35204171, 2022). "Furthermore, common TLR4 and NOD2 gene variants alter the maternal inflammatory responses, which damage the inflammatory response to endotoxin, and are associated with severe hypertensive disorders in pregnancy." (PMID 36496806, 2022). "Therefore, we investigated the progression of hypertension after the activation of the microglia and TLR4 resulted from the increase in AT1R, further studied the effects of the AT1R inhibitor losartan on SBP, superoxide production, and activity of the microglia." (PMID 34829655, 2021). "Nevertheless, further studies are needed in order to confirm the roles of TLR4 in BP regulation as well as whether this process is linked to the integrity of the BBB, which could leverage our understanding of autonomic diseases, especially hypertension." (PMID 31191352, 2019). "Additional studies are required to identify TLR4 mediated signaling mechanisms involved in ROS generation and macrophage activation and delineate the crosstalk between oxidative stress and renal inflammation to identify potential therapeutic targets to reduce hypertension induced renal damage." (PMID 28743964, 2017). "Therefore, one possible mechanism by which TLR4 is activated in hypertension could be via upregulation of HMGB1." (PMID 25879545, 2015). "Therefore, we hypothesize that TLR4 signaling in the PVN of the brain might be one of the main factors for the establishment of hypertension and cardiac remodeling observed in the SHR rats." (PMID 25879545, 2015). "In addition, the underlying molecular mechanisms in TLR4 mediated inflammatory response in hypertension have never been studied." (PMID 25879545, 2015). "Therefore, to investigate whether TLR4 signaling within the PVN contributes to inflammatory response seen in hypertension, we measured the gene and protein expression of TNF-α, IL-1β and iNOS in the PVN tissue." (PMID 25879545, 2015). "Therefore, enhanced expression of brain TLR4/NF-κB may play an important role in cerebral pathology induced by hypertension." (PMID 24223475, 2013). "This study also highlights the importance of inflammasome activation in hypertension, with concurrent involvement of the NLRP3/IL-1β and TLR4/NF-κB pathways in promoting kidney injury and inflammation." (PMID 40433411, 2025).
Hypertension (continued). "LPS stimulates toll-like receptor 4 (TLR4), which induces the production of proinflammatory cytokines involved in the pathogenesis of hypertension and anxiety." (PMID 37273529, 2023). "A recent study has found that both TLR4-TRIF and TLR3-TRIF pathways mediate Ang II-induced cardiac hypertrophy, whereby only the TLR3-TRIF pathway is required for Ang II-induced hypertension." (PMID 37113698, 2023). "There are 11 subtypes of TLRs, and the participation of TLR2, TLR3, TLR4, TLR7, and TLR9 receptors in hypertension has been described." (PMID 35371030, 2022). "TLR4 is one of the crucial receptors of HMGB1; the persistent activation of TLR4 induces the damage of kidney, cardiovascular, and CNS tissue in hypertension." (PMID 34970076, 2021). "Bragina E.Y., Goncharova I.A., Freidin M.B., Zhalsanova I.Z., GomboevaD.E., Nemerov E.V., Puzyrev V.P. Analysis of haplotypes ofCAT, TLR4, and IL10 genes in bronchial asthma patients comorbidwith arterial hypertension." (PMID 35088020, 2021). "Overall, these results suggest that the TLR4/MyD88/NF-κB pathway is a bridge between RAS, SNS and hypertension, and provides a novel treatment therapeutic for hypertension and cardiac hypertrophy caused by hypertension." (PMID 33324685, 2020). "Similarly, continuous subcutaneous infusion of Ang II increased the level of brain TLR4 in the Ang II-induced hypertensive rat model, activated myocardial inflammation and increased sympathetic activity, both of which are responsible for hypertension and cardiac hypertrophy." (PMID 33324685, 2020). "In summary, abundant evidence shows that 2K1C renovascular hypertensive rats had significant upregulation of TLR4/MyD88/NF-κB signaling transduction within the PVN and contributes to the pathogenesis of hypertension." (PMID 31708733, 2019). "Our results demonstrated that pravastatin decreased the hypertension, urine protein level, and the incidence of FGR of PE-like rat model by ameliorating the exacerbated TLR4/NF-κB activation in placenta from LPS rats’ model." (PMID 30008464, 2018). "However, whether resistin and TLR4 play a role in hypertension is largely unknown." (PMID 26917360, 2016). "In the present study, we investigated the effects of bilateral inhibition of TLR4 within the hypothalamic PVN of the brain of SHR rats, which are well established as a genetic model of human essential hypertension." (PMID 25879545, 2015). "In fact, TLR4, the major receptor for LPS present in Gram-negative bacteria, highlights the potential role of oral microbiota and dysbiosis on hypertension." (PMID 37892006, 2023). "Although we have not analysed the mechanisms by which TLR4 blockade improves the IL-1β-induced endothelial dysfunction, the reduction of oxidative stress might contribute to this effect, as has been reported in the hypertension-associated endothelial dysfunction." (PMID 36937865, 2023). "Besides, TLR4 activation increases oxidative stress and activates MCP-1 expression, resulting in cardiac hypertrophy in Ang II-induced hypertension." (PMID 37113698, 2023). "Furthermore, NKA α2 shRNA restored the balance of pro- and anti- inflammatory cytokines as well as decreased the TLR4, MyD88, and NF-κB p65 expression in the PVN during the development of hypertension." (PMID 35204171, 2022). "BBR (1.25, 2.5, and 5 μmol/L) could inhibit the apoptosis of aortic endothelial cells isolated from SHR, decrease the expression of TLR4, MyD88, NF-κB, IL-6 and TNF-α, and have a certain protective effect on hypertension-induced vascular endothelial injury." (PMID 33815112, 2021). "TLR4 signaling is a major source of pro-inflammatory cytokines, such as TNF-α, and blockade of TLR4 in the brain has been shown to prevent cardiac dysfunction in experimental models of heart failure and hypertension." (PMID 25811788, 2015).
Hypertension (continued). "The role of the brain in the initiation and progression of all forms of hypertension is well established, but the role of brain TLR4 in progression of hypertension has never been explored." (PMID 25879545, 2015). "Therefore, we investigated the role of TLR4 within the paraventricular nucleus (PVN; an important cardioregulatory center in the brain) in an animal model of human essential hypertension." (PMID 25879545, 2015). "Downregulation or inhibition of TLR4 has been shown to reduce angiotensin II-induced VSMC migration and proliferation, and this would contribute to explain the beneficial effects of TLR4 blockade in vascular remodelling and mechanical alterations observed in hypertension." (PMID 36937865, 2023). "Hence, NKAα2 regulates the TLR4/MyD88/NF-κB signaling pathway and induces the PVN neuroinflammatory responses in the PVN, thus elevating blood pressure and sympathetic activity in the context of salt-induced hypertension." (PMID 35204171, 2022). "We observed that, compared with matched non-diabetic/non-hypertensive donors (age: 58.12 ± 2.6 years; and, BMI: 25.84 ± 0.99), the presence of type 1 diabetes/hypertension (age: 58.12 ± 2.6 years; and, BMI: 26.97 ± 0.90) associates with an increase in the expression levels of MD2 but not TLR4." (PMID 32694567, 2020). "More importantly, we found that chronic blockade of TLR4 lowers MAP in diabetic animals (mmHg: 79 ± 1.87 vs. 104.3 ± 2.46; treated vs. non-treated), suggesting that this receptor might contribute to prolonged type 1 diabetes-induced hypertension." (PMID 32694567, 2020). "Activation of TLR4 leads to downstream release of inflammatory modulators including TNF-α, IL-1β and MCP-1.Moreover, previous studies demonstrated that inflammation plays a crucial role in the pathogenesis of hypertension, and the development and progression of renalfibrosis." (PMID 26556241, 2015). "Therefore, the aim of this study was to investigate whether TLR4 activation, due to increased RAS activity, contributes to hypertension and the functional vascular alterations observed in this pathology." (PMID 25093580, 2014). "Toll-like receptor 4 (TLR4) signaling contributes to inflammatory cardiovascular and renal diseases, but its role in Aldo-induced hypertension and renal damage is not clear." (PMID 26556241, 2015). "By contrast TLR4 SNP rs4986790 cases had no increase of SBP, PP and hypertension with BMI." (PMID 26435700, 2015).
pancreatic cancer (110 papers, 2012 to 2026). "Apart from the expression of TLR4 by cells of the immune system, TLRs have been linked to several cancers including pancreatic cancer." (PMID 28572836, 2017). "Furthermore, the TLR4/NF-κB axis has been associated with the enhanced invasion and metastasis of pancreatic cancer cells." (PMID 40214484, 2025). "In pancreatic cancer, B7-H3 has been found to promote tumor invasion and metastasis through the TLR4/NF-κB pathway." (PMID 40519928, 2025). "To gain more insights into the impact of TLR4 inhibition on pancreatic cancer cells, we also performed transcriptome sequencing on TAK‐242‐treated PANC‐1 cells." (PMID 40696496, 2025). "Conversely, Lactobacillus casei and Lactobacillus reuteri have been shown to inhibit the proliferation and migration of pancreatic cancer cells by suppressing TLR4." (PMID 40161368, 2025). "We found that TLR2 and TLR9, along with TLR4, play an important role in the growth of pancreatic cancer." (PMID 38390872, 2024). "Our results are consistent with findings from other groups showing that blocking TLR4 or TLR9 potentiates pancreatic cancer cells to apoptosis." (PMID 38390872, 2024). "A recent study in pancreatic cancer shows that the increased invasion of TAM2s can promote the EMT process of pancreatic cancer by activating TLR4/IL-10 signaling pathway in cancer cells, reducing E-cadherin and increasing the expression of Vimentin." (PMID 38693304, 2024). "In the most recent exploration, it was found that L. casei and L. reuteri were able to inhibit TLR4, which in turn stopped pancreatic cancer cells from multiplying, migrating, invading, and inducing macrophages to become M2 polarized." (PMID 39582101, 2024). "Since TLR4 promotes CTCs migration in pancreatic cancer and blocking TLR4 signaling inhibits CTCs migration and invasion, TLR4 appears to be a potential therapeutic target." (PMID 37874534, 2024). "TLR4 protein expression in pancreatic carcinoma and cholangiocarcinoma patients was significantly higher in SIBO+ than SIBO− patients." (PMID 38790992, 2024). "Pancreatic cancer cells promoted M2 macrophage polarization in the TME, and our results showed that L. casei & L. reuteri treatment ablated the pro-M2 effect of pancreatic cancer cells on macrophages by inhibiting TLR4." (PMID 37904102, 2023). "Tumour-promoting protein PAUF secreted by cancer cells promotes the migration of human pancreatic cancer cells through TLR4/MyD88 signal." (PMID 38052785, 2023). "L. casei & L. reuteri alleviate pancreatic cancer by inhibiting TLR4 to promote macrophage M1 polarization and regulate gut microbial homeostasis." (PMID 37904102, 2023). "A recent study showed that the immune checkpoint protein B7 homolog 3 (B7-H3) promotes invasion and metastasis of pancreatic cancer cells by inducing TLR4 expression." (PMID 37112730, 2023). "L. casei & L. reuteri inhibited the proliferation, migration, invasion of pancreatic cancer cells and pancreatic cancer cell-induced M2 polarization of macrophages by suppressing TLR4." (PMID 37904102, 2023). "TLR4 was significantly overexpressed in pancreatic cancer cells and tissues and boosted the proliferation of pancreatic cancer cells by upregulating anti-apoptotic Bcl-2." (PMID 37904102, 2023). "As a double-edged sword, TLR4 exerted pro-tumor or anti-tumor effects in different cancers, while in pancreatic cancer, TLR4 mainly promoted tumor progression." (PMID 37904102, 2023). "In pancreatic cancer, the expression of TLR2 and TLR4 is mainly increased, and is associated with higher mortality,while TLR9 shows a downward trend in pancreatic cancer." (PMID 38110966, 2023). "A previous study showed that Toll-like receptor 4 triggers angiogenesis in pancreatic cancer cells by regulating PI3K/Akt signaling." (PMID 36114448, 2022). "In pancreatic cancers, PA activates the TLR4/ROS/NF-κB/MMP9 signaling pathway, increasing cancer aggressiveness." (PMID 36422271, 2022).
pancreatic cancer (continued). "Triptolide inhibited Toll-like receptor 4 (TLR4)/NF-κB signaling to enhance pancreatic-cancer-cell-line sensitivity to gemcitabine, which resulted in decreased tumor cell proliferation, viability and xenograft tumor volume." (PMID 36700235, 2022). "In vitro, knockdown of the LPS receptor TLR-4 in pancreatic cancer cell lines dramatically decreased Yap protein levels while in the presence of autophagic stress." (PMID 35326559, 2022). "The current study not only shows that PAUF can bind directly to TLR4 on pancreatic cancer (PC) cell surfaces and promote cell migration exclusively through the MyD88-dependent pathway." (PMID 36232715, 2022). "Coculturing M2-polarized TAMs with pancreatic cancer cells resulted in high expression of Toll-like receptor 4 (TLR4) compared with culturing the M2-polarized TAMs alone." (PMID 35501802, 2022). "LPS has been shown to promote the development of pancreatic cancer by blocking the MyD88-dependent pathway while blocking TLR4 and MyD88-independent pathway has a protective effect on pancreatic cancer." (PMID 36003766, 2022). "This study aimed to investigate if PAUF elicits autocrine effects on pancreatic cancer (PC) cells through TLR4, a receptor that is overexpressed on PC cells." (PMID 36232715, 2022). "Recently, a polysaccharide isolated from Strongylocentrotus nudus eggs (SEP) has been shown to inhibit pancreatic cancer growth through TLR4/MAPKs/NF-κB pathway signals and activate NK cells in vitro and in vivo." (PMID 34884547, 2021). "TLR4 and MyD88 were found to be significantly increased in a concentration-dependent manner in PANC-1 and BxPC-3, which hinted that stimulating TLR4 led to positive feedback in pancreatic cancer cells." (PMID 34718325, 2021). "To further confirm LPS inducing PD-L1 expression in PDAC, we firstly detected TLR4 and PD-L1 basal expression in four pancreatic cancer cell lines and normal pancreatic epithelia cell line." (PMID 34718325, 2021). "In pancreatic cancer, M2-polarized TAMs expressing Toll-like receptor 4 (TLR4) promoted EMT via TLR4/IL-10 signaling." (PMID 33922795, 2021). "TLR4 upregulation has been found also in pancreatic cancer where it plays a central role in tumor progression." (PMID 34884547, 2021). "It has been demonstrated that stromal leukocytes from pancreatic cancer patients show high TLR4 expression levels." (PMID 34884547, 2021). "CD276 can also help promote pancreatic carcinoma metastasis and infiltration by activating the TLR4–NF-κB signaling pathway, via upregulated expression of IL-8 and VEGF." (PMID 34367975, 2021). "Since markers such as integrin β-1 or vimentin play an essential role in adhesion and invasiveness of pancreatic carcinoma cells, we analysed the relationship between light-induced TLR4 activation and integrin β-1 and vimentin expression." (PMID 34502140, 2021). "Regarding immune inhibitors, IDO-1 regulates the immune response via NF-κB; CD276 can help promote pancreatic carcinoma metastasis and infiltration by activating the TLR4–NF-κB signaling pathway, via upregulated expression of IL-8 and VEGF." (PMID 34367975, 2021). "On the contrary, when IL-10 is secreted by M2-like TAMs in co-culture with pancreatic cancer cells, it promotes epithelial–mesenchymal transition of cancer cells via toll like receptor 4 (TLR4)/IL-10 signaling." (PMID 32326073, 2020). "Experimental evidence in a mouse model of PC proved that the activation of TLR4 can promote pancreatic tumor development through activating the NF-κB and MAPK signaling pathways in immune cells." (PMID 32461969, 2020). "Another group demonstrated that activation of TLR4 signaling led to IL-10 production in M2-polarized macrophages promoting EMT of pancreatic cancer cells via its regulation on mesenchymal markers, vimentin, and Snail." (PMID 32283687, 2020).